IL1B (interleukin 1 beta)
Diseases named in the same sentence as IL1B in open-access papers (continued):
Sharing a sentence is not in itself a finding about the gene and the disease.
melanoma (continued). "Metastatic melanoma cell lines do not secrete IL-1β but promote IL-1β production from macrophages." (PMID 28060744, 2017). "Furthermore, IL-1β precursor protein expression in melanoma cells was negligible, and these cells did not secrete the active, cleaved form of the IL-1β protein." (PMID 28450382, 2017). "In contrast, non-metastatic melanoma cell lines secreted less or no IL-1β." (PMID 24273542, 2013). "Interestingly, our results show that IL-1β is not decreased in the TME of melanoma-bearing Nlrp3-/- animals (data not shown), indicating that NLRP3 ablation may promote tumor regression and MDSC subset re-programming via an IL-1β-independent mechanism." (PMID 36032139, 2022). "In addition, melanoma exosome-delivered miR-125b-5p contributes to the phenotypic transformation of macrophages with the induction of C-C motif chemokine ligand 1(CCL1), CCL2, and IL-1β expression, thus leading to myeloid cell recruitment and cancer-associated inflammation." (PMID 36612077, 2022). "However, the roles of IL-1β in the stemness maintenance of HNSCC and melanoma are largely unknown." (PMID 32547321, 2020). "NLRP1 is considered to be a tumor suppressor, but aberrant NLRP1 inflammasome activation due to gain-of-function mutations has been associated with cancers and autoimmune diseases, which could reasonably explain why some melanoma cell lines, if not all, are capable of secreting IL-1β." (PMID 33396632, 2020). "Because we found that melanoma cells do not produce significant amounts of IL-1β themselves and melanoma cells have previously been shown to stimulate monocyte differentiation into macrophages, we hypothesized that melanoma cells might trigger IL-1β production and secretion in macrophages." (PMID 28450382, 2017). "Thus, in the present study, macrophagic IL-1β and TNF-α were observed to promote VEGF-C expression in TAMs, as well as melanoma lymph node metastasis, suggesting that inhibiting the signaling between tumor cells and TAMs may be required to inhibit lymphangiogenesis and lymph node metastasis." (PMID 25120672, 2014). "Dedifferentiated melanoma cells have been reported to secrete multiple cytokines in greater quantity, notably CCL2, CCL5 and IL-1β, either without inflammatory stimuli or when stimulated with TNFα." (PMID 39736644, 2024). "Moreover, CY12-RP2 could inhibit melanoma lung metastasis, and abrogated the immunosuppressive effects of PDPN by increasing the proportion of CD3 + CD4 + T cells, CD3 + CD8 + T cells, CD49b + Granzyme B + NK cells, and CD11b + CD86 + M1-like macrophages and the levels of IL-1β, TNF-α, and IFN-γ." (PMID 38167452, 2024). "In conclusion, we demonstrated that IL-1β induces the activation of NF-κB p65/RelA, but not p105, which contributes to IL-1β-induced MMP-3 expression in canine melanoma cells." (PMID 36445856, 2022). "siRNA-mediated gene silencing of IL-1β decreased pJNK in A375 and WM793 melanoma cells without affecting total JNK levels, confirming that JNK is activated by IL-1β in melanoma." (PMID 32252279, 2020). "As control served the double-stranded DNA mimic dAdT that signals NLRP3 independently via the DNA sensor absent in melanoma 2 (AIM2), still requiring the adapter molecule ASC as well as caspase-1 for the processing of IL-1β." (PMID 29403480, 2017). "Although IL-1β is known to be expressed in certain cancer cells, we have excluded the role of tumor-derived IL-1β in building the immunosuppressive microenvironment, as IL-1β is not detectable in B16F10 melanoma cells in WT and KO mice (data not shown)." (PMID 25706411, 2015). "B16F10 mouse melanoma cells, which do not express pro-IL-1β, NLRP3 and AIM2 (data not shown), were chosen to generate B16F10-IL-1β, B16F10-pro-IL-1β (expressing non-secretable IL-1β) and B16F10-vector cells." (PMID 23065753, 2012). "However, GCP‐2 released from senescent fibroblasts can—independent of IL‐1β signaling—enhances CREB activation in melanoma cells and thereby enforces melanoma progression." (PMID 41258756, 2025).
melanoma (continued). "Similarly, IL1B was expressed at much higher levels in iCAFs derived from melanoma, while TGFB3 and LGALS9 were strongly expressed in iCAFs from BCC and SCC but not melanoma." (PMID 39516494, 2024). "However, in melanoma cells treated with UK356618 (50 nM), IL-1β failed to mediate cell migration, implying that MMP-3 is involved in IL-1β-induced melanoma cell migration." (PMID 36445856, 2022). "In a mouse model of intravenous injection of B16-F10 melanoma cells, researchers found that mice lacking NLRP3 had a significant decrease in lung metastases compared with wild-type mice and that the pathway was independent of caspase-1 and IL-1β." (PMID 31242947, 2019). "Furthermore, when IL-1β and TNF-α were used at a non-toxic level, they enhanced peritoneal lymph node colonization by melanoma cells." (PMID 25120672, 2014).
Anxiety (310 papers, 2012 to 2026). Intense feelings of nervousness, tension, or panic often arise in response to interpersonal stresses. "Studies have highlighted that proinflammatory interleukin-1β (IL-1β) is associated with deficits in spatial memory, disrupted sleep-wake cycles, increased anxiety, and reduced social engagement in cats." (PMID 41268300, 2025). "Overactive platelets are associated with chronic inflammation, further exacerbating anxiety symptoms by releasing factors such as angiotensin II and IL-1β, which amplify inflammatory responses in the nervous system." (PMID 41144483, 2025). "Behaviourally, elevated IL-1β secretion is associated with anxiety, fear, and exacerbated emotional responses towards acute and chronic stress." (PMID 41451408, 2025). "Mechanistically, the anti-anxiety action of quercetin is closely associated with the inhibition of interleukin-6 (IL-6) and interleukin-1β (IL-1β) expression in the hippocampus." (PMID 40520201, 2025). "Studies have shown that ATP/P2X7R-initiated microglia in the ipsilateral hippocampus can drive anxiety-depressive-like behaviors associated with trigeminal neuralgia via IL-1β." (PMID 38370420, 2024). "P2X7 is also involved in brain monocyte aggregation associated with repeated social failure, IL-1β mRNA expression in enriched myeloid cells, plasma IL-6, and anxiety-like behavior." (PMID 38370420, 2024). "The HFD in rats induced anxiety-like behavior associated with neuroinflammation, overproduction of IL-1β and IL-6, cerebral oxidative stress, increased lipoperoxidation, inhibition of enzymatic and non-enzymatic antioxidants, and increased ROS levels." (PMID 38279738, 2024). "was associated with circulating inflammation (IL-1β) and behavioral outcomes (lethargy and anxiety-like behavior)." (PMID 37266023, 2023). "When co-injected with IL-1β, LP-211 treatment prevented glial reactivity, the down-regulation of myelin-associated proteins, and the apparition of anxiety-like phenotypes." (PMID 36335540, 2023). "Using EPM criteria alone showed that higher levels of circulating IL-1β are associated with lower anxiety-like behavior." (PMID 37064304, 2023). "Other studies on animals also have demonstrated that upregulation of IL-1β in the brains of murine stress models is associated with the development of anxiety." (PMID 37692303, 2023). "It has also been linked to circulating inflammatory (IL-1β) and behavioral outcomes, such as lethargy, and anxiety-like behavioral." (PMID 35845787, 2022). "A splenic increase in Il1β and Tlr4 with cortical Vcam expression strongly associated with the anxiety-like behavior while splenic IL-10 associated with IL-1β from both the PFC and cortex, predicted depressive-like behavior." (PMID 34248950, 2021). "The results showed that CCI caused mechanical hyperalgesia and depressive and anxiety-like behaviors in rats and neuroinflammation in the amygdala, such as an increased protein level of TNFα and IL-1β and activation of astrocytes." (PMID 34025342, 2021). "Increased levels of IL-1β and IL-6 are associated with increased stereotypy, impaired cognitive abilities, anxiety, and decreased social interactions." (PMID 32443651, 2020). "In this study, we genotyped the IL-1β gene (rs16944) to observe the relationship of the polymorphism and anxiety state in an Italian population sample." (PMID 32377159, 2020). "In the obese group, there were significant associations of anxiety and mood disorders with mRNA levels of inflammatory mediators displaying a lower expression, except for IL-1β in the VAT." (PMID 30504920, 2018). "For instance, interleukin (IL)-1β is associated with stress-induced macrophage recruitment and heightened anxiety-like behavior in males, and female rats exhibit greater basal IL-1β and IL1r1 expression in cortical and hippocampal tissue compared to males." (PMID 29194444, 2017). "Altogether, these data are consistent with the idea that EAE anxiety-like behavior is linked to IL-1β-mediated CB1R dysfunction." (PMID 27589957, 2016).
Anxiety (continued). "In line with this, a single icv injection of IL-1β caused anxiety in mice and abrogated the sensitivity of CB1Rs controlling GABA synapses in the striatum." (PMID 27589957, 2016). "Our results point to CB1R as involved in EAE-associated anxiety and establish a previously unrecognized link between mood alterations and IL-1β-dependent inflammatory synaptic dysfunction in EAE and, possibly, MS." (PMID 27589957, 2016). "For instance, a previous study demonstrated that P. berghei-infected mice exhibit anxiety-like symptoms associated with increased brain levels of IL-1β and TNF, and histopathological changes in brainstem, cerebrum and hippocampus." (PMID 24180288, 2013). "Moreover, nuclear factor kappa-B (NF-κB), tumor necrosis factor-α (TNF-α) and IL-1β produced by activated microglia in the BLA are associated with anxiety- and depressive-like behaviors in mice." (PMID 41276822, 2025). "Furthermore, inflammatory processes are triggered by anxiety, which is caused by high levels of pro-inflammatory cytokines such as IL-6, IL-1β and TNF-α." (PMID 38255283, 2024). "Furthermore, anxiety triggers inflammatory processes by causing high levels of pro-inflammatory cytokines such as IL-6, IL-1β, and TNF-α." (PMID 39720795, 2024). "Several genes are associated with anxiety, including the interleukin (IL)-1β gene." (PMID 37448433, 2023). "As evidence suggests, IL-1β may serve as a marker for the initiation of a proinflammatory response specifically targeting anxiety-like behaviors caused by chronic stress, leading to a cascade of inflammatory factor responses." (PMID 37692303, 2023). "It is concluded that synbiotic nutritional supplements can improve anxiety, stress, and sleep quality, particularly in sportspeople, which appears to be linked to an improved immuno-neuroendocrine response in which IL-1β, CRH, and dopamine are clearly involved." (PMID 33923663, 2021). "Similarly, anxiety-like behavior during experimental MS has been linked to both an IL-1β-dependent alteration of endocannabinoid and GABAergic striatal signaling and a tumor necrosis factor α (TNF-α)-induced alteration of striatal glutamatergic transmission." (PMID 33922780, 2021). "Moreover, A carriers, according to HAM-A, had significantly higher risk to be anxious compared to noncarriers (p < 0.01; OR = 5.90 (1.73; 20.16)), showing an interaction between IL-1β polymorphism and anxiety state." (PMID 32377159, 2020). "The IL-1β and IL-6 were positively associated to the anger and the anxiety state, respectively." (PMID 29445205, 2018). "Central blockade of interleukin-1β (IL-1β) reversed the anxiety-like phenotype of EAE mice, an effect associated with the concomitant rescue of dopamine (DA)-regulated spontaneous behavior, and DA-CB1R neurotransmission, leading to the rescue of striatal CB1R sensitivity." (PMID 27589957, 2016). "This may be important since elevated CNS pro-inflammatory cytokines, including IL-1β and/or TNFα, have been associated with increased anxiety, decreased cognition, and altered social behaviors." (PMID 25212412, 2014). "Notably, in perinatal bacterial infection models, microglial Iba1 immunoreactivity was associated with increased anxiety and elevated brain IL-1β levels that corresponded with decreased memory after lipopolysaccharide (LPS) challenge." (PMID 25212412, 2014). "In our study, the positive association of anti-inflammatory, neuroprotective, and emotional regulatory IL-10 with anxiety and activity, along with the inverse association between IL-1β and anxiety, may represent this regulatory balance and buffered inflammatory load in these aging cats." (PMID 41268300, 2025). "Additionally, anxiety symptoms can improve in healthy adults where the IL-1β gene is a risk factor." (PMID 37448433, 2023). "However, IL-1β levels are associated with anxiety symptoms’ severity in patients with MDD." (PMID 34576215, 2021).
Anxiety (continued). "We therefore propose that the anxiolytic action of BGOS on LPS injected mice was the result of the prebiotic’s anti-inflammatory properties, which suppressed the increase of IL-1β, and subsequent elevation of 5-HT2ARs that may underlie post-inflammatory anxiety behaviour." (PMID 26476141, 2016). "It is known that cytokines, including IL-1β, play the critical role in modulating the activity of the amygdala, particularly in the context of stress and anxiety-related behaviours [for review 39]." (PMID 40373086, 2025). "This suggests that one possible mechanism through which BECLIN-1 disruption alters nociceptive hypersensitivity and anxiety-like behaviors in male mice is through altering injury-related immune responses, including the release of IL-1β." (PMID 39809538, 2025). "Animal studies also found that COX2 inhibition is associated with a reduced increase in the proinflammatory cytokines TNFα and IL1β together with lower anxiety and cognitive decline." (PMID 40352929, 2025). "Cytokines, particularly pro-inflammatory interleukin-1β (IL-1β) and tumour necrosis factor-alpha (TNF-α), have been implicated in heightened depressive-like and anxiety-like behaviours." (PMID 41451408, 2025). "A study found that quercetin administration decreases brain concentrations of inflammatory factors, including IL-1β, IL-6, and NF-kB, and mitigates anxiety-like behaviors in rats with lipopolysaccharide-induced chronic neuroinflammation." (PMID 40333577, 2025). "Among them are anxiety behavior, learning, hippocampus-dependent forms of memory, and the IL-1β concentrations in the cerebral cortices of male and female C57BL/6 mice." (PMID 39941015, 2025). "For instance, chronic mild stress significantly increases the expression of both the Nlrp3 inflammasome and IL-1β in the hippocampus, resulting in depressive- and anxiety-like behaviors in rats." (PMID 41276822, 2025). "Anxiety was positively associated with higher BCS, creatinine, and IL-10, and negatively associated with IL-1β." (PMID 41268300, 2025). "Collectively, our findings indicate that BPA triggers anxiety-like behaviors and pyroptotic death of nerve cells via the NF-κB/IL-1β/NLRP3/Caspase-1 pathway." (PMID 38941031, 2025). "The cats with lower IL-1β had increased odds of exhibiting more severe anxiety, as assessed by the FCDRC, whereas IL-10 emerged as a positive predictor of greater severity of changes in both the anxiety and activity domains." (PMID 41268300, 2025). "They found that individuals carrying the IL-1β A allele, a variant associated with hyperinflammatory responses, showed greater reductions in anxiety and IL-1β serum levels following probiotic intake." (PMID 40732886, 2025). "Studies have shown that the experimental administration of tumor necrosis factor alpha (TNF-α), interleukin-1 beta (IL-1β), and IL-6 results in a depressive effect, including anxiety, drowsiness, and fatigue, in humans." (PMID 40746874, 2025). "In the female group, statistically significant results were observed in volunteers with moderate and severe anxiety levels, with emphasis on D-dimer, CK-MB, NT-proBNP, and IL-1β." (PMID 40563433, 2025). "In numerous animal models, MCC950 has been shown to reduce IL-1β and IL-18 levels in the hippocampus and amygdala, decrease microgliosis, and reverse anhedonia, depressive, and anxiety-like behaviors." (PMID 41008651, 2025). "Gyps significantly suppresses proinflammatory mediators (IL-1β, IL-6, NF-κB) in LPS-induced neuroinflammation and anxiety models, demonstrating therapeutic potential for neuroinflammation-associated anxiety behaviors." (PMID 41181612, 2025). "Specifically, 7 days after intracerebroventricular (i.c.v.)infusion of IL-1β, male rats exhibited elevated anxiety levels in the OFT and EPM test, along with an increased expression of GFAP and elevated GABA content in PVN astrocytes." (PMID 40141416, 2025).